TNF (tumor necrosis factor)
Diseases named in the same sentence as TNF in open-access papers (continued):
Sharing a sentence is not in itself a finding about the gene and the disease.
periodontitis (continued). "Periodontitis pathogens can stimulate cells to produce inflammatory factors such as IL-1β, IL-6, and TNF-α and enter the body circulation system through the broken gingival epithelium in periodontal pockets, causing bacteremia, or ectopic colonization in other organs." (PMID 37808891, 2023). "Thus, TNF-α secretion during periodontitis is dependent on inflammatory caspase activation following recognition of a pathogenic or harmful effect." (PMID 36794778, 2023). "Indeed, higher levels of pro-inflammatory cytokines (IL-1β, IL-6, TNF) were found in blood and gingival fluid in obese subjects with periodontitis compared to normo-weighted subjects with periodontitis." (PMID 37894804, 2023). "IL-6, nitric oxide, IL-1B, TNF-α and osteoprotegerin are among the most present biomarkers in patients with periodontitis, and may be used in the future as a monitoring of periodontal disease." (PMID 37026605, 2023). "The plasma concentrations of IL-1 and TNF-α increased after the induction of periodontitis." (PMID 36840029, 2023). "Additionally, significant differences in TNFα and IL-6 levels were found between patients in accord with the mild, moderate, and severe periodontitis stages." (PMID 36599866, 2023). "However, once periodontitis has occurred, the release of tumour necrosis factor (TNF), interleukins (ILs), and other inflammatory factors by inflammatory cells in response to external stimuli can mediate secondary tissue damage." (PMID 37724115, 2023). "IL-6 and TNF-α are common inflammatory cytokines that are elevated in patients with periodontitis." (PMID 37645411, 2023). "An increasing number of studies have shown that TNF-α preconditioning enhances the therapeutic effects of exosomes derived from MSCs in various diseases, including bone defects, periodontitis, retinal ganglion injury, acute liver failure and urethral stricture." (PMID 36978165, 2023). "Increased levels of IL-1β and TNF-α in the GCF occur in periodontitis." (PMID 37623272, 2023). "Our results showed that the presence of SB significantly inhibited inflammatory cell infiltration and prevented the increase of the relative mRNA expression of TNF-α, IL-1β, and IL-6 in both in vivo and in vitro models, which indicates that SB effectively inhibited the inflammation in periodontitis." (PMID 36846719, 2023). "The presence of inflammatory mediators in periodontitis, such as IL-1, IL-1 β, IL-4, IL-6, IL-8, IL-10, TNF and IFN-γ, together with macrophages sensitized by M. leprae in the bloodstream can exacerbate the host’s immune response, triggering the leprosy reaction." (PMID 37418096, 2023). "Similarly, chitosan hydrogels loaded with DPSC-derived CEVs (DPSC-EVs) reduced the expression of IL-23, IL-1α, TNF-α, IL-12, IL-1β, IL-27, and IL-17 in periodontitis tissues." (PMID 36982864, 2023). "Because anti-TNF-α drug treatment is commonly used to control the inflammatory process, such therapy may also be relevant for the management of periodontitis." (PMID 36671633, 2023). "In periodontitis, the expression of inflammatory cytokines, such as interleukin-1 beta (IL-1β), interleukin-6 (IL-6), and tumor necrosis factor-alpha (TNF-a), is increased, and it is closely related to the destruction of periodontal tissue and alveolar bone loss." (PMID 37240020, 2023). "After 8 weeks of periodontitis in mice treated with oral MAG (50 mg/kg body weight, once a day), it was found that MAG significantly inhibited alveolar bone loss, TNF-α production in gingival epithelial cells, and the phosphorylation of NF-κB and JAK1-STAT1/3 pathways." (PMID 37508406, 2023). "The rationale behind those hypotheses was that patients with periodontitis exhibit higher systemic levels of inflammatory mediators such as interleukin (IL-2, IL-6) and tumor necrosis factor (TNF-α)." (PMID 37735212, 2023). "IFN-γ, IL-1β, and TNF-α are elevated in chronic periodontitis compared to healthy controls." (PMID 35189698, 2022).
periodontitis (continued). "Therefore, the proinflammatory cytokines TNF-α, IL-1β, and IL-6 play a key role in the occurrence and development of periodontitis." (PMID 36546940, 2022). "Additionally, it was discovered that knocking down lncZFY-AS1 reduced inflammatory factors TNF-α, IL-1β, and IL-6 in the periodontitis model." (PMID 35659193, 2022). "In a study where nano-emulsion formulation was used to treat periodontitis, the histopathological results for the rats showed a significant reduction of TNF-α, which reveals the important role of anti-inflammatory and antibacterial activity for the treatment of periodontal disease." (PMID 36050950, 2022). "B. lactis HN019 application could markedly decrease the levels of IL-1β and the ratio of RANKL/OPG in rats with periodontitis and metabolic syndrome and could downregulate the expression of TNF-α and IL-6 in rats only with periodontitis." (PMID 35402306, 2022). "However, DIO mice with periodontitis showed sluggish inflammatory response with reduced expression of TNF-α level compared with that of DIO mice." (PMID 36060644, 2022). "Other soluble receptors or antagonists to IL‐1 or TNF‐α were used in monkey models with experimentally induced periodontitis and either showed a significant reduction of inflammatory cell infiltrates, reduction of osteoclast numbers, or reduced attachment and bone loss." (PMID 34626163, 2022). "Periodontitis is a chronic systemic inflammatory disease, and neutrophils play a pivotal role in early lesions, while inflammatory cytokines (e.g., IL-1β and TNF-α) are crucial in the pathogenesis." (PMID 36275028, 2022). "In addition, high HIF-1α and NFATc1 levels were detected in severe periodontitis and gingival crevicular fluid samples of severe periodontitis patients, suggesting a role for the TNF-α/HIF-1α/VEGF pathway in the pathogenesis of periodontitis." (PMID 36142220, 2022). "Our previous study found that the expression of GLP-1R was detected on hPDLCs, and LIRA could inhibit the expression of IL-6 and TNF-α on the experimental periodontitis." (PMID 35845316, 2022). "Treatment of PsO with TNF-α inhibitors can also slow down the progression of periodontitis." (PMID 35371044, 2022). "IL-6 and TNF-α level were regulated by miR-21 in macrophages of periodontitis." (PMID 35931990, 2022). "Consequently, a high expression profile involving proinflammatory cytokines, IL‐1, IL‐7, IL‐10, IL‐17, IL‐8, TNF‐α, and monocyte chemoattractant protein‐1, were detected both in patients with periodontitis and those with COVID‐19." (PMID 35578891, 2022). "It has been reported that PDLSCs from periodontitis patients (P-PDLSCs) showed impaired osteogenesis and regeneration ability, which could be mimicked in normal PDLSCs (N-PDLSCs) treated by 10 ng/ml TNF-α." (PMID 35063024, 2022). "One study indicated that bacteria contributing to periodontitis might stimulate the production of pro-inflammatory cytokines by oral epithelial cells, namely IL-6, IL-8, and TNF-α, thus resulting in the progression of UC." (PMID 36248861, 2022). "Furthermore, TNF-α was found at higher levels in both saliva and serum of subjects with periodontitis compared to the levels in healthy subjects." (PMID 35845957, 2022). "Multiple mediators may have systemic effects on bone formation and bone resorption, the proinflammatory cytokine TNF- α、 IL-1 and IL-6 have been shown to be increased in patients with periodontitis." (PMID 36584175, 2022). "An overexpression of miRNA-146 in patients with rapidly progressive aggressive periodontitis was shown to be accompanied by a reduction in the levels of TNF-α, IL-1β, and IL-6, which suggests the existence of a negative feedback loop between mi-146 and pro-inflammatory cytokine synthesis." (PMID 35269617, 2022).
periodontitis (continued). "Hence, this study investigated the therapeutic potential of nano-emulsion of mangosteen rind extract in a mucoadhesive gingival patch on a periodontitis model induced by P. gingivalis and its effect on TNF-α, IL-10, and RANKL expression." (PMID 36050950, 2022). "LPS is a potent stimulator of inflammation, can produce proinflammatory cytokines such as TNFα, IL-6, and IL-1β, resulting in disturbance of periodontal ligament cell differentiation, and further leads to deep periodontal tissue destruction and periodontitis." (PMID 35546327, 2022). "TNF-α and other inflammatory factors are locally released, attach to plaques and promote osteoclast activation, particularly under inflammatory osteolysis conditions in periodontitis." (PMID 36467684, 2022). "Another explanation may be that telomere dysfunction can activate the production and secretion of inflammatory factors such as IL-6 and TNF-α, leading to the development of periodontitis." (PMID 36601105, 2022). "Our result showed that periodontitis induced by ligation with P. gingivalis could upregulate TNF-α levels in lung tissue under an LF diet at 10 days." (PMID 36060644, 2022). "In periodontitis, inflammatory markers, such as C-reactive protein (CRP), and pro-inflammatory cytokines, such as Tumor Necrosis Factor α (TNFα), are increased, which eventually may be associated with cognitive decline in AD patients." (PMID 36289921, 2022). "Plumbagin inhibits chronic periodontitis by downregulating the TNF-α, IL-1β, and IL-6 expressions." (PMID 36589679, 2022). "During acute and chronic inflammation in periodontitis, high amount of TNF-α generated by activated macrophages may lead to periodontal tissues degeneration." (PMID 35903322, 2022). "TNF-α and IL-1β are critical inflammatory mediators that play an important role in the interactions between PDLSCs and immune cells, which are significant in the development of periodontitis (Pan, Wang, and Chen, 2019)." (PMID 35464198, 2022). "The present study was a cross-sectional study that involved patients with slight or moderate chronic periodontitis and examined the relationships between the parameters of different periodontal health statuses of the subjects in addition to salivary TNF-α, sTNF-R1, and sTNF-R2 levels." (PMID 35200250, 2022). "TNF-α contributes to the onset of periodontal inflammation, such as periodontitis." (PMID 35200250, 2022). "Increased levels of TNF-α and IL-6 were also reported in human mothers with periodontitis." (PMID 35269617, 2022). "Furthermore, in the present study, the levels of miR-1246 in saliva of patients with chronic periodontitis were positively correlated with the levels of IL-1β, IL-6, IL-17, and TNF-α, indicating a correlation between the two." (PMID 35942384, 2022). "In this study, we have been unable to determine how TNF-α and IL-6 are regulated by PPARα in periodontitis, i.e., whether via the PPAR response element (PPRE) or via other PPARα target genes." (PMID 35293424, 2022). "In both studies, saliva samples were collected during the 3rd trimester and authors found a higher prevalence of periodontitis as well as significantly higher levels of TNF-α, IL-1β, total antioxidant capacity (s-TAC) and CRP, particularly when GDM was diagnosed." (PMID 36432584, 2022). "As an example, the overexpression of miRNA-146a in periodontitis patients was also accompanied by a decrease in the release of pro-inflammatory cytokines (TNF-a, IL-1B, and IL-6), suggesting that the elevation of miRNA-146a regulates pro-inflammatory cytokines through a negative feedback loop." (PMID 36142220, 2022). "This imbalance leading to increased IL-1 and TNF-α release may contribute to exacerbate periodontitis in DM." (PMID 35052857, 2022). "Thus, TNF-α examination can improve understanding of the pathogenesis of periodontitis and GDM and its assessment in the treatment process can result in better disease control." (PMID 35016229, 2022).
periodontitis (continued). "Elucidation of the dynamics of sTNF-R1 and sTNF-R2 against TNF-α in oral conditions, including saliva, is expected to contribute to the development of new procedures for the diagnosis and treatment of periodontal diseases, such as gingivitis and periodontitis." (PMID 35200250, 2022). "A large number of macrophages can be seen in the periodontal tissue of patients with periodontitis, and a large number of proinflammatory factors and bone resorptive factors, such as interleukin 1β, interleukin 6 (IL-6), and TNF-α, can be detected in gingival crevicular fluid." (PMID 35586136, 2022). "Of note, in experimental mouse models of periodontitis, TLR4 loss of function inhibits the deleterious effect of periodontitis on the insulin signaling pathway, evidenced by the increased ratio of pAkt/Akt and decreased levels of TNF-α." (PMID 35327570, 2022). "TNF-α or INF-γ is the main inflammatory cytokine related to periodontitis." (PMID 35063024, 2022). "Collectively, these findings suggest that reduced levels of CRP, IL-6, TNFα, and IL-1β after treatment of periodontitis could restore eNOS activity and NO bioavailability, resulting in improved endothelial dysfunction." (PMID 35874771, 2022). "Increased GCF VEGF and TNF-α levels in both chronic and aggressive forms of periodontitis might suggest the role of the TNF-α/VEGF pathway in the pathogenesis of periodontal diseases." (PMID 35571048, 2022). "In line with this, PBMCs from patients with periodontitis stimulated in vitro with LPS of Escherichia coli, have also demonstrated a proinflammatory secretory pattern with higher levels of the cytokine’s TNF-α and IL-6, among others, in comparison with PBMCs from healthy individuals." (PMID 35300329, 2022). "Higher secretion of TNF-α was observed from OBMCs when compared to PBMCs of periodontitis patients." (PMID 33672708, 2021). "Salivary IL-1β and TNF-α were also assessed as pro-inflammatory molecules related to periodontitis." (PMID 34950607, 2021). "TNF-α induces apoptosis in gingival epithelial cells in periodontitis." (PMID 33616153, 2021). "Nevertheless, during periodontitis, cytokines, such as Il-1β, IL-6 and TNF-α, are secreted in response to bacterial insult and could sustain the neuroinflammation process after passage through the blood–brain barrier." (PMID 34501984, 2021). "Although periodontitis patients were excluded, the presence of plaque may have induced gingival inflammation, acting as a confounding factor for raised TNF-α levels." (PMID 34299679, 2021). "The potential role of TNF-α in osteoclastogenesis is of significance in periodontitis." (PMID 33673606, 2021). "Thus, this study aimed to investigate the IL-1β, CXCL8, and TNF-α levels in GCF in patients with different degrees of periodontitis and PISF in patients with healthy implants." (PMID 33726736, 2021). "In addition, mice with periodontitis induced by ovariectomy showed significantly higher serum levels of TNF-α than mice that underwent ovariectomy alone." (PMID 34445604, 2021). "The main finding of the present study was that H2S stimulated the secretion of IFN-γ, IL-6, IL-17, TNF-α, IL-12p40, and IL-12p70, from PBMCs of both periodontitis patients and healthy controls, while the reverse was seen for IL-1Ra, that is, H2S decreased the secretion." (PMID 34408814, 2021). "In addition, we found that the mRNA expression of TNF-α was significantly increased in the isotype-periodontitis group compared to that in the control group." (PMID 34481478, 2021). "Although there are controversial effectiveness signals with TNF inhibitors in improving chronic periodontitis, all papers about anti-IL-6 therapy clearly demonstrated articular, systemic, and also periodontal benefits with TCZ without any periodontal specific treatment." (PMID 33672771, 2021). "Furthermore, periodontitis decreased macrophages, TNF-α, and INF-γ expression in a mouse model of chronic obstructive pulmonary disease (COPD)." (PMID 34445604, 2021).
periodontitis (continued). "Thus, our finding that the injection of Exo-TNF significantly decreased TRAP-positive cells in our mouse periodontitis model strongly suggests that miR-1260b is involved in the regulation of osteoclastogenesis." (PMID 33359765, 2021). "The MAPK pathway is the upstream signaling intermediate to many inflammatory cytokines such as TNF-α, IL-1β, IL-6, and prostaglandin E2, and the blockage of this pathway could be beneficial for treating inflammatory diseases like chronic periodontitis and AD." (PMID 33869630, 2021). "One of the limitations in our study was the evaluation of solely the clinical outcomes; so, further studies are required to evaluate the therapeutic effects of nano‐curcumin on gingivitis and periodontitis by the means of assessing inflammatory mediators such as TNF‐α and interleukins." (PMID 32954688, 2021). "LPS stimulation mainly augmented the expression levels of proinflammatory cytokines, including interleukin IL-1 beta (IL1β), tumor necrosis factor-alpha (TNFα), and IL-6, resulting in an inflammatory response and destruction of periodontal tissue during periodontitis." (PMID 34899921, 2021). "Therefore, the effects of ginsenosides on IL-6 and TNF-α, the major inflammatory cytokines involved in periodontitis, and the role of HO-1 were evaluated." (PMID 33917440, 2021). "Moreover, the proinflammatory cytokines, such as IL-1β, IL-6, and TNF-α, have been used as biomarkers to diagnose periodontitis and peri-implantitis." (PMID 34931168, 2021). "Patients with periodontitis have higher serum and saliva levels of TNF-α than healthy individuals." (PMID 33861790, 2021). "In obese subjects with periodontitis, pro-inflammatory cytokines (Interleukin-1β (Il-1β), Interleukin-6 (Il-6), Tumor Necrosis Factor α (TNF-α)) were found in greater quantities in the blood and also in the crevicular gingival fluid compared to normo-weighted subjects with periodontitis." (PMID 33919425, 2021). "Previous studies confirmed that the expression levels of TNF-α and IL-6 were positively correlated with the severity of periodontitis, which was significantly increased at the site of periodontal inflammation, and its level was significantly reduced after treatment." (PMID 34819109, 2021). "However, persistently high levels of TNF-α are observed in several oral diseases such as oral lichen planus, periodontitis, and oral squamous cell carcinoma, where the presence of macrophages is heavily implicated in the disease process." (PMID 34210153, 2021). "The effect of IL-17 and IFN-γ on periodontal gingival tissues and alveolar bone suggests their proresorption roles for periodontitis in vivo, which might partly be explained by their stimulatory effect on IL-1β, TNF-α, and IL-6." (PMID 34395635, 2021). "In the present study, the AT1 blockade was shown to reduce the levels of proinflammatory cytokines, such as IL-1ß, IL-6 and TNF-α, but was not able to prevent the bone loss, a hallmark of periodontitis progression." (PMID 34884653, 2021). "Moreover, the level of TNF-α in PISF in patients with implants was significantly higher than in those with healthy periodontitis or mild periodontitis." (PMID 33726736, 2021). "However, overexpression of PTEN in experimental periodontitis mice attenuated the expression of IL-1, IL-6, and TNF-α." (PMID 34445604, 2021). "Since supernatants obtained from OBMCs of periodontitis patients contain significant levels of pro-inflammatory cytokines such as TNF-α, IL-6 and IL-1β, these cytokines may be inhibitory for the induction of IFN-γ." (PMID 33672708, 2021). "TNF-α did decrease; however, levels were still higher than periodontitis-only groups." (PMID 34950607, 2021). "Furthermore, according to a study by Kobayashi and colleagues, tocilizumab (TCZ) also ameliorates periodontal inflammation in RA with periodontitis as TNF inhibitors do." (PMID 33672771, 2021).